RNVU1-28 (RNA, variant U1 small nuclear 28)
Gene: Small nuclear RNA gene on chromosome 1 (144,560,666 to 144,560,829, reverse strand). Ensembl gene ENSG00000277918.
Gene Ontology:
Molecular function: pre-mRNA 5'-splice site binding
Biological process: mRNA 5'-splice site recognition
Cellular component: U1 snRNP
Homologues: Paralogues in human: RNU1-1 (99% identical), RNU1-2 (99% identical), RNU1-27P (99% identical), RNU1-28P (99% identical), RNU1-3 (99% identical), RNU1-4 (99% identical), RNVU1-18 (99% identical), RNVU1-29 (99% identical), U1 (99% identical), RNVU1-7 (99% identical), RNVU1-31 (98% identical), RNU1-89P (96% identical), and 133 more.